CCL21 (C-C motif chemokine ligand 21)
Diseases named in the same sentence as CCL21 in open-access papers (continued):
Sharing a sentence is not in itself a finding about the gene and the disease.
breast cancer (continued). "In vitro, endothelin activation of ETA correlated with increased CCR7 cell surface expression in MCF-7, SKBR3 and MDA-MB-231 human breast cancer cell lines, which enhanced MCF-7 invasion of Matrigel towards CCL21 or CCL19 only in the presence of endothelin." (PMID 35203305, 2022). "CCL21 stimulation of MDA-MB-231 and MDA-MB-361 human breast cancer cell lines in vitro enhanced intracellular filamentous actin, while inducing pseudopodia and invasive responses." (PMID 35203305, 2022). "Targeting a single paracrine signaling pathway, e.g., CCL21/CCR7 or CXCL12/CXCR4, has been shown to reduce lymphatic metastasis in murine models of breast cancer." (PMID 34885152, 2021). "Epithelial–mesenchymal transition phenotype was also determined during stimulation of breast cancer cell lines HCC1428, MCF-7 and MDA-MB-231 with CCL21." (PMID 34160019, 2021). "CCL21 inhibits tumor growth and enhances survival by CD3 T lymphocytes, particularly in cancer cells with CCR7 expression in mammary tumor-bearing mice." (PMID 34160019, 2021). "Investigation using a highly invasive breast cancer cell line, MDA-MB-231, also showed increased expression of CCL21 in the synergic stimulation." (PMID 34671596, 2021). "The silencing of CCR7 decreased the in vitro proliferation, migration and invasion of CCL21/CCL19-induced MCF-7 and MDA-MB-231 breast cancer cells." (PMID 32340161, 2020). "For example, the expression of CCL19 and CCL21, ligands of CCR7, was significantly increased in lymph nodes of breast cancer patients." (PMID 32253815, 2020). "It has been reported that lymph nodes can produce CCL21 and the interaction between CCL21 and CCR7 can regulate the directional migration to promote the lymph node metastasis of breast cancer, suggesting that CCR7 is involved in cell migration." (PMID 31217907, 2019). "Chemokines with well-known functions in mammary cancer include CCL2, CCL5, CCL19, CCL20, CCL21 and CCL22." (PMID 30572845, 2018). "We have shown that a molecular cross-talk between breast cancer cells and LEC via the CCL21/CCR7 chemokine/ chemokine receptor axis plays a major role in breast cancer associated lymphangiogenesis." (PMID 28056899, 2017). "In the present model, breast cancer MDA-MB-231 cells and NKL3 cells express the surface CCR7 receptor for CCL21 chemokine which is a potent chemoattractant able to bind to PDPN." (PMID 28416768, 2017). "The impact of the CCL21/CCR7 axis in the molecular mechanism of the adhesion of NKL3 cells and of MDA-MB-231 breast cancer cells was reduced in a hypoxic tumor environment." (PMID 28416768, 2017). "Addtionally, CCL21/CCR7 chemokine axis regulates the expression and secretion of VEGF-C in human breast cancer cells, and contributes to LECs lymphangiogenesis and breast cancer-induced lymphangiogenesis." (PMID 27166194, 2016). "To characterize the role of CCL21/CCR7 in situ, we used a panel of breast cancer tissues (n = 105) collected from the primary tumor site." (PMID 25744065, 2015). "The expression analysis of CCL21/CCR7 pair and lymphatic endothelial cell (LEC) markers in breast cancer specimens was performed by means of quantitative real-time PCR." (PMID 25744065, 2015). "Next, the inhibitory effect of let-7a was determined by using synthetic anti-let-7a oligo-nucleotides in MCF-7 breast cancer cells, which express a high level of let-7a and a low level of CCR7, with a high level of CCL21 expression." (PMID 22251626, 2012). "Chemokines CCL19, CCL20 and CCL21 and their receptors CCR6 and CCR7, were assessed as potential biomarkers of metastatic dissemination in primary breast cancer." (PMID 21624121, 2011). "The CXCR4, CCR7, CXCL12, CCL21, and EGFR biomarkers were analyzed along with ER, PR, and HER-2/neu in breast cancer tissue microarray (TMA) specimens, including 200 primary breast cancer specimens by immunohistochemistry." (PMID 20181250, 2010).
breast cancer (continued). "Out of all the known chemokine receptors, breast cancer cells specifically express active CXCR4 and CCR7, the ligands of which are HCXCL12 and CCL21, respectively." (PMID 20181250, 2010). "This study investigated the expression of CXCR4, CCR7, CXCL12, CCL21, and EGFR to illustrate the role of these biomarkers in breast cancer metastasis and prognosis." (PMID 20181250, 2010). "Mutant-CCL21 induced leukocyte chemotaxis in diffusion gradients but did not stimulate trans-endothelial migration of breast cancer cells." (PMID 34298676, 2021). "Overall, CCL19, CCL21, GPR183, P2RY13, and PENK were potential protective factors in breast cancer." (PMID 32195260, 2020). "Activation of CCL21/CCR7 axis could induce tumor progression and metastasis in melanoma, breast cancer and colorectal cancer." (PMID 31523177, 2019). "Compared with healthy volunteers, the extremely high serum levels of MMP-9 and CCL21 in patients with colon cancer, of CCL11 in patients with gastric cancer, of CCL2/MCP-1 in patients with breast cancer and of CXCL13 in patients with liver cancer have been reported." (PMID 31754081, 2019). "Our analysis suggests that CCL19, CCL21 and IL7 signaling play an important role in attracting and activating immune cells in the breast cancer microenvironment and might help convert immune cold cancers to immune hot." (PMID 30967156, 2019). "Lymphatic endothelial cells have been reported to highly express CCL21, whereas its receptor CCR7 is highly expressed in breast cancer cells and melanoma cells and predicted to be the mechanism by which breast cancer and melanoma preferentially metastasize to lymph nodes." (PMID 30705401, 2019). "Moreover, CCL21/CCR7 signalings VEGF-C expression and secretion and promotes breast cancer-induced lymphangiogenesis via LEC activation." (PMID 29599774, 2018). "Analysis of a cohort of 234 breast cancer patient samples showed a correlation of tumors with aggressive invasive properties and a signature of genes expressed by ILC3, enriched for CXCL13, CCL19, CCL21, and the receptors CXCR5 and CCR7." (PMID 27882334, 2016). "Since our in vitro and in vivo studies have established the roles of CCR7/CCL21 and VEGFR3/VEGF-C axes in breast cancer induced lymphangiogenesis, we have postulated that CCR7 and VEGF-C expressions will be noticeably different in tumor tissues when compared to their non-tumor counterparts." (PMID 25744065, 2015). "Prior to the investigation of the role of CCL21/CCR7 pair in VEGF-C production, we have screened the constitutive expression of CCR7, CCL21, and VEGF-C in two well differentiated, luminal type (T47D, MCF-7) and two poorly differentiated basal type (Hs578t, MDA-MB-231) breast cancer cell lines." (PMID 25744065, 2015). "Similarly, CCL21, through its receptor CCR7, triggers actin polymerization, pseudopodia formation, and the directional migration and invasion of breast cancer cells, particularly to lymph nodes, where CCL21 is highly expressed." (PMID 25165728, 2014). "However, CCL21 was more highly expressed in MDA-MB-231 and MCF-7 cell lines than in the other five breast cancer cell lines." (PMID 22251626, 2012). "Unlike CXCL12, however, CC chemokine ligand-21 (CCL21) - the ligand for CC chemokine receptor-7 (CCR7) - is highly expressed in the lymph nodes of breast cancer patients." (PMID 20181250, 2010). "Moreover, as staining for CXCL12 and CCL21 (or CXCR4 and CCR7) was tightly linked in the group of primary tumors and lymph node metastasis tumors in this study, it is likely that a shared mechanism may account for variations in expression levels of both molecules in breast cancer." (PMID 20181250, 2010). "This must necessarily lead to an organotropism; e.g., breast cancer cells express high levels of CXCR4 and CCR7, which are responsible for the metastasis formation in LN, lung, liver, and KM, as these organs are rich in corresponding ligands CXCL12 and CCL21 [Chambers3471]." (PMID 35326690, 2022).
breast cancer (continued). "Intriguingly, CathD has also been shown to selectively degrade macrophage inflammatory protein (MIP)-1α (CCL3), MIP-1β (CCL4), and SLC (CCL21) that, in turn, may affect the generation of the anti-tumoral immune response, the migration of human breast cancer cells, or both processes." (PMID 26610586, 2015). "Moreover, CCL21/CCR7 chemokine axis has the ability to promote lymphatic endothelial cells proliferation, migration, as well as tube formation in vitro, and this axis also regulates the expression of lymphangiogenic factor VEGF-C by breast cancer cells." (PMID 25744065, 2015). "The relatively small sample size and heterogeneity of the tumor types however, may not be an accurate look into the overall picture of CCL21 expression in breast cancer." (PMID 24762633, 2014). "Stimulation of HS578T-Hyg breast cancer cells with CCL21 did not result in AKT phosphorylation." (PMID 23667660, 2013). "Patient cohort study also declared that in primary tumors, CCL21 up-regulation and RORgt+ ILC3 infiltration were correlated to enhanced draining lymph node metastasis in basal-like breast cancer but not in HER2+ or luminal A/B subtype." (PMID 39877637, 2025). "By contrast, treatment of HS578T-Hyg breast cancer cells with the PI3K inhibitor Ly294002 did not alter the cells migratory activity (both control and CCL21 treated cells), which is in view with Western Blot studies showing no AKT phosphorylation in CCL21 stimulated HS578T-Hyg cells." (PMID 23667660, 2013). "Moreover, because the PI3K inhibitor Ly294002 also blocked the CCL21 induced MAPKp42/44 phosphorylation in HS578T-Hyg cells, but did not alter the cells migratory behavior these data suggest that MAPKp42/44 signaling is not involved in the migration of HS578T-Hyg breast cancer cells." (PMID 23667660, 2013).
melanoma (60 papers, 2010 to 2025). A malignant, usually aggressive tumor composed of atypical, neoplastic melanocytes. "Among the five cell lines used, tumor growth of B16–F10 and YUMM1.7 was decreased in Ccl21a-KO mice, whereas that of LLC and EO771 was unchanged, and that of MC38 was increased, suggesting that the effect of CCL21-Ser deficiency is selective for melanoma." (PMID 37664721, 2023). "Loss of CCR7 or blockade of C-C motif chemokine ligand 21 (CCL21)/CCR7 axis abolished the pro-migration effect of PTX on B16F10 melanoma cells." (PMID 35280672, 2022). "The overexpression of CCR7 on melanoma cells caused a greater migration of these cells towards LECs, and the use of a CCL21-neutralising antibody stopped their migration in vitro." (PMID 34830780, 2021). "The receptor CCR7 and its ligand CCL21 have been implicated in the lymphatic spread of tumor when CCR7 is expressed by melanoma cells and when CCL21 is expressed by lymphatic endothelial cells." (PMID 28952543, 2017). "A progressive decrease in CCL21 production in TDLN of mice with growing transplanted melanomas was also previously associated with impaired recruitment of naïve TL in LN, independent of LN metastasis." (PMID 21811640, 2011). "In the Amela-melanoma model, reduction of T-zones was associated with a loss of gp38+ FRCs and CCL21 in those zones." (PMID 21811640, 2011). "Although CCL21 can also establish an immunosuppressive tumor microenvironment, it was recently shown that tumor-associated lymphatic vessels also facilitate naïve T cell recruitment into melanoma tumors through CCL21 production." (PMID 29527513, 2018). "CCL21 expression by melanoma tumors in mice has been shown to be associated with an immunotolerant microenvironment, which included the induction of lymphoid-like reticular stromal networks, an altered cytokine milieu, and the recruitment of regulatory T cell populations." (PMID 24212647, 2011). "The occurrence of this effect of IR on the CCR7-CCL19/CCL21 axis was confirmed in our murine model of melanoma." (PMID 38951172, 2024). "In contrast, in another study, CCL21-Ser produced by murine melanoma cells induced peritumoral LN-like structures and recruited immunosuppressive cells, enhancing the melanoma growth." (PMID 37664721, 2023). "The expression of CCL21 in cancer cells including melanoma, liver cancer, and prostate cancer cells, induces immune responses and inhibits tumor growth." (PMID 37664721, 2023). "A 12-chemokine gene expression signature including CCL2-5, CCL8, CCL18, CCL19, CCL21, CXCL9-11, and CXCL13 has been previously reported to serve as a predictor for the presence of TLS in melanoma specimens in association with improved OS." (PMID 37435077, 2023). "Taken together, these results suggest that endogenous CCL21-Ser supports melanoma growth in vivo by maintaining Treg function and suppressing antitumor immunity by CD8+ T cells." (PMID 37664721, 2023). "CCL21-Ser in melanoma and lung carcinoma cells suppressed tumor growth by developing blood vessels similar to the high endothelial venules in LNs, leading to an enhanced antitumor immunity by mobilizing naïve lymphocytes to the tumor tissue." (PMID 37664721, 2023). "In contrast, dextran-coated IONPs reduced MSC’s cellular expression of CD9, showed unaltered CCL21 secretion by MSCs (compared to control) and therefore unaltered chemoattraction and migration of melanoma cell line." (PMID 35103937, 2022). "Essentially, in human MSCs, ionomycin increased cellular CD9 expression, which reduced CCL21 secretion by MSCs, which lessened chemoattraction and thereby decreased the migration of melanoma cell line." (PMID 35103937, 2022). "In this case, CCR7-expressing malignant melanoma cells were undergoing chemotaxis to CCL21 produced by lymphatic endothelial cells." (PMID 35203305, 2022). "They used short hairpin RNA (shRNA) to knockdown endogenous CCL21 secretion in murine melanoma cells and found that CCL21low tumors contained lower amounts of TGF-β1." (PMID 35904690, 2022).
melanoma (continued). "The CCR7/CCL21 pathway coordinates the migration of melanoma cells towards and into lymphatic vessels." (PMID 34830780, 2021). "In mouse models of melanoma and lung cancer, the LN-like vasculature in tumors, characterized by the expression of PNAd and chemokine CCL21, induced by effector lymphocytes allows naive T cells to enter tumors and enhance antitumor immunity." (PMID 34394083, 2021). "Downregulation of CCL21-expression has been reported in TDLNs in mouse models of melanoma, both in FRCs and in HEVs." (PMID 33430113, 2021). "The recruitment of Treg cells and myeloid-derived suppressor cells (MDSCs) to lymphoid aggregates in mouse B16 melanomas expressing CCL21 was found to correlate with the promotion of tumor growth." (PMID 34394083, 2021). "We have already discussed how melanoma is able to exploit the CCR7/CCL21 axis, but efforts have also been made to use this axis for therapeutic benefit." (PMID 34830780, 2021). "Human lymph nodes express CCL21, while melanoma cells produce its receptor, CCR7, which is a key molecule mediating metastasis of many cancers." (PMID 33430277, 2021). "Previous studies have shown that B16F10 melanoma regulate CCL21 dependent T cell recruitment from HEV blood vessels in tumor draining LN but the role of L-selectin was not explored." (PMID 31249570, 2019). "Because DC/CCL21 vaccines have been tested in clinical trials for patients with lung cancer and melanoma, our studies provide the foundation for future trials of DC/CCL21 vaccination in patients receiving pre-transplant conditioning regimens." (PMID 29617362, 2018). "We then imaged co-cultures of the target melanoma cells with OT-I T-cells that were pre-cultured on uncoated substrates or on substrate-immobilized CCL21 + ICAM1." (PMID 29942308, 2018). "Most studies identify CCL21 as a tumor-suppressing molecule, but there are also some studies show that CCL21/CCR7axis promotes growth and metastasis of many tumor types including melanomas, breast, thyroid, colon, head, and neck cancers." (PMID 27783999, 2017). "The secretion of CCL21 was found to be correlated with invasiveness and immune tolerance in murine melanoma." (PMID 28036019, 2016). "Early data from these studies show the known chemotactic selectivity of CCL21 with the accumulation of T cells in biopsies from one of the melanoma injection sites." (PMID 24810425, 2014). "In murine model of melanoma, intratumoral injections of DC-CCL21 three times in two weeks led to tumor growth inhibition that was significantly better than either control DCs or CCL21 alone." (PMID 24810425, 2014). "Nonetheless, we believe caution should be exercised in interpreting the implications of CCL21 in tumor growth and anti-tumor immunity, especially given the ongoing clinical trials of CCL21 in lung and melanoma patients." (PMID 24810425, 2014). "CCL21 secreting B16-F10 melanoma cells and related tumor environment seemed to recruit functional activated DCs, while promoted differentiation of naïve T cells to Treg cells, which was normally induced by immature DC." (PMID 24810425, 2014). "The correlation between CCR7 expression and lymph node metastasis was further verified by administration of neutralizing anti-CCL21 antibodies that markedly blocked lymph node metastasis of CCR7 expressing B16 melanoma cells." (PMID 23667660, 2013). "The role of CCL21/CCR7 signaling in the recruitment and accumulation of Tregs in tumors has been described in one study using B16 melanomas engineered to express higher levels of CCL21." (PMID 23874342, 2013). "A recently closed Phase I clinical trial in melanoma applied intradermal injections of adenovirus-CCL21 transduced class I peptide-pulsed DCs." (PMID 24967094, 2013). "DC genetically engineered to secrete high-levels of CCL21 (DC.CCL21) and injected directly into B16 murine melanomas promote strong extranodal T cell cross-priming/recruitment into the TME, even in LTα −/− mice that lack SLO." (PMID 24348473, 2013).